CD47 (CD47 molecule)
Diseases named in the same sentence as CD47 in open-access papers (continued):
Sharing a sentence is not in itself a finding about the gene and the disease.
tumor (continued). "Herein, we constructed an adenovirus-based tumor vaccine expressing a mouse nanobody antagonist of CD47 fused with the IgG2a Fc protein (mCD47nb-Fc) and investigated its antitumor effects." (PMID 35837100, 2022). "As the “don't eat me” signalling molecule, CD47 prevents macrophage‐mediated phagocytosis of tumour cells." (PMID 35665592, 2022). "CD47 is a membrane protein expressed in a variety of malignant tumors and hematopoietic cells, which plays a key role in immune escape and tumor progression." (PMID 35646646, 2022). "We evaluated the expression of CD47 in patients with CC in different tumor stages in different ways." (PMID 36611344, 2022). "In a murine tumor model, adaptive T cell responses were observed after treatment with CD47 antibodies." (PMID 36389667, 2022). "Similar to mice with a single tumor, radiotherapy and CD47 blockade had an enhanced local inhibitory effect on the irradiated tumors compared to individual treatments (left)." (PMID 36411318, 2022). "Meanwhile, several CD47-SIRPα directed treatments are being studied in combination with tumor-directed monoclonal antibodies, which are of the human IgG1 isotype." (PMID 35865547, 2022). "Treatment with antibodies to CD47 on tumor cells promoted antibody-dependent cellular phagocytosis of tumor cells mediated by macrophages." (PMID 35454882, 2022). "Several studies demonstrated immune evasion by tumor cells through the expression of a multitude of receptors, such as CD47 and programmed cell death ligand 1 (PD-L1)." (PMID 35035479, 2022). "In vitro studies reveal that CD47/CD20 BsAbs stimulate tumor cell phagocytosis in a CD20-dependent approach." (PMID 35978372, 2022). "STI-6643 has been affinity-engineered to maintain the ‘on-target/on-tumor’ activity but reduce the ‘on-target/off-tumor’ binding to CD47." (PMID 35664753, 2022). "Similar to CD47-blocking antibody, suppressing integrin activation has consequently limited the macrophage dissemination on the surface of tumor cells, allowing tumor cells to evade phagocytosis." (PMID 35054787, 2022). "Next, we have correlated the proportions of CD47+ tumor cells in the center of the tumor and in the periphery of the tumor in each histological subtype." (PMID 36171566, 2022). "In particular, magrolimab (Hu5F9-G4, ONO-7913) is a humanized monoclonal antibody that binds CD47 at low nanomolar affinity and is built on an IgG4 scaffold to minimize Fc-mediated effector toxicity for non-tumor cells expressing CD47." (PMID 36293358, 2022). "We investigated the expression of CD47 in tumor tissues of patients with CUC in different stages and analyzed the sensitivity of different immunohistochemical scores to define the cut-off most significantly associated with tumor biology and progression." (PMID 36611344, 2022). "Consistent with our observations from in vitro experiment, LAT2 depletion greatly reduced the basal and doxorubicin-induced CD47 expression in tumor tissues." (PMID 36274066, 2022). "Effects on tumor cells are mediated by TSP-1 through the interaction with CD36 as well as CD47, a member of the immunoglobulin superfamily." (PMID 35054787, 2022). "Inhibition of CD47-SIRPα further enhanced the destruction of IgA-opsonized tumor cells by neutrophils in vitro as well as in vivo." (PMID 35884427, 2022). "Expressed CD47 on tumor cells can bind to SIRPα on the macrophages and inhibit phagocytosis of tumor cells." (PMID 36018888, 2022). "Early successes in inducing tumor cell phagocytosis and inhibition of tumor growth in vitro and in vivo led to multiple preclinical and early clinical studies to assess the efficacy and safety of CD47-targeted anticancer therapies." (PMID 36171566, 2022). "In previous studies, anti-CD47 antibody has been used for targeted imaging and tumor-specific drug delivery in bladder urothelial carcinoma (BUC)." (PMID 35295998, 2022).
tumor (continued). "Systemic antitumor effects and immune memory were also observed in immunocompetent mice following in situ vaccination with the anti-CD47 tumor vaccines; tumorigenesis was completely inhibited in these mice after tumor re-challenge." (PMID 35837100, 2022). "Analyses of the HOS-derived tumor tissues showed that doxorubicin increased macrophage activation with M1-polarity, IL-18 secretion, and CD47 expression." (PMID 36274066, 2022). "The SIRPαFc fusion protein can block the immunosuppressive CD47-SIRPα signal between macrophages and tumor cells as a decoy receptor and has demonstrated its immunotherapeutic efficacy in various tumors." (PMID 35422796, 2022). "Co-targeting PD-1/PD-L1 and CD47 with mAb combinations showed increased anti-tumor responses in clinical studies." (PMID 36009390, 2022). "The ligand CD47, which is overexpressed on the tumor, has an Ig-like domain in its extracellular region as well as five transmembrane domains." (PMID 35865547, 2022). "The interaction of CD47 with SIRPα gives macrophages a “don’t eat me” signal, inhibiting phagocytosis and allowing tumor cells to evade immune surveillance." (PMID 35205760, 2022). "This question remains crucial considering the importance of CD8+ T cells in boosting and maintaining anti-tumor responses upon anti-CD47 therapy as observed in preclinical animal models." (PMID 35664753, 2022). "To investigate how the biological behavior of SGC tumors is affected by CD47 expression, we have also correlated the expression status with the grade and stage of the tumor." (PMID 36171566, 2022). "Tumor-infiltrating lymphocyte (TIL) analysis revealed up-regulation of CD47 in CD8+ T cells and T cell exhaustion." (PMID 36018888, 2022). "In our study, analysis of NSCLC patients showed that membrane CD47 overexpression by cancer cells was noted in two-thirds of tumor samples, where one-third expressed CD47 in more than 50% of cancer cells." (PMID 35406573, 2022). "Interim results from a Phase I/II trial of anti-CD47 IgG2 mAb AO-176 demonstrated a good tolerability profile and possible anti-tumour activity, with 1 PR and 7 SD from 27 patients with advanced solid tumours." (PMID 35020853, 2022). "In immunohistochemical analysis, the CD47 protein expression level was higher in both non-muscle-invasive and muscle-invasive (stage ≥T2) UTUCs than that in normal uroepithelium, and the localization of CD47 protein was the tumor cell membrane." (PMID 35295998, 2022). "The inhibition of exosome secretion or uptake via the knockdown of RAB27A, a regulator of exosome secretion, reduces the expression of CD47 in tumour cells, promotes phagocytosis by M1 macrophages in tumour tissues, and suppresses tumour progression." (PMID 36298556, 2022). "MYC specifically activates the expression of glutamine transporter and glutaminase in tumors, thereby regulating the reprogramming of glutamine metabolism in tumors.At the same time, MYC also regulates the expression of PD-L1 and CD47 in the tumor cells." (PMID 35897036, 2022). "For instance, increased TSP-1 and CD47 interaction enhanced tumor progression in T-cell lymphoma and breast cancer, but induced drug resistance in thyroid cancer." (PMID 35869130, 2022). "Similar to tumor cells, erythrocytes also highly express CD47 to protect themselves from the attack of macrophages, thus prolong the circulation time." (PMID 35874757, 2022). "accumulation of anti-CD47 antibody conjugated with IR700 in tumor cells was achieved in 24 h after injection." (PMID 37448778, 2022). "Our findings provide new insights linking CD47 with numerous tumor prognoses, effects and mechanisms of targeting CD47 in anti-tumor immunity." (PMID 35697717, 2022). "Subsequently, we reincubated the uroepithelium of the same sample and the tumor with anti-CD47-Alexa Fluor 790, rinsed with sterile saline, and imaged again." (PMID 35295998, 2022).
tumor (continued). "Since tumor-cell phagocytosis by monocytes/macrophages has been extensively described as a key mechanism of action of CD47/SIRPα blocking molecules, we have explored the phagocytic activity of these cell populations in the TME." (PMID 35538512, 2022). "This is attributed to physiological resistance mechanisms such as high expression of CD47 signaling and physical disorders, including abnormal tumor vasculature during tumor evolution." (PMID 36384524, 2022). "Such combinations include those with tumour‐targeted opsonizing antibodies, systemic therapy, epigenetic drugs, other immunomodulatory T‐cell‐targeted therapeutics or dual immunomodulatory CD47 bispecific antibodies." (PMID 35908284, 2022). "Velcro-CD47 already proved its ability to enhance macrophage phagocytosis of tumor cells in vitro as well as to target the monocyte subpopulation specifically, and its putative anticancer efficacy will be assessed in further pre-clinical models." (PMID 35054787, 2022). "As a result, off-tumor toxicities such as anemia and thrombocytopenia have been observed in patients subjected to anti-CD47 treatment in clinical studies." (PMID 36970051, 2022). "The anti-phagocytic inhibitory signal was removed or reduced through downregulation of both CD47 and SIRPα gene expression on tumor cells and macrophages, respectively." (PMID 35418166, 2022). "Tumor-bearing mice were treated with either a human IgG4 mAb isotype control or anti-CD47 clones STI-6643 or Hu5F9 at 30 mg/kg (mpk) for 6 doses over a 2-week period." (PMID 35664753, 2022). "We thus tested whether treatment with NI-1701 would enhance ADCP of tumor cells by TAMs/monocytes in vivo but also by tumor-associated DCs, as recent reports highlighted the pivotal role of DCs at triggering antitumor T-cell response following CD47/SIRPα blockade." (PMID 35538512, 2022). "Researchers found a boom in CRT expression on tumor cells, but the overexpression of CD47 counterbalances the possible phagocytosis it mediated." (PMID 35978433, 2022). "In a couple of cancer types, the level of CD47 expression was inversely related to tumor purity in LGG (r = − 0.086, P = 0.049) and UCEC (r = − 0.116, P = 0.007)." (PMID 35697717, 2022). "CD47 is overexpressed on a variety of tumor cells and activates “don’t eat me” signaling by binding to SIRPα, causing immune escape of tumor cells from the mononuclear phagocyte system." (PMID 35890175, 2022). "Previous studies found that CD47, a transmembrane glycoprotein, is present in a variety of cells, that its expression is significantly increased in tumor cells, and there is also some increased expression in normal ADMSCs." (PMID 35845399, 2022). "Antibodies blocking the CD47-SIRPα interaction increased phagocytosis of macrophages and cytotoxicity of PMNs, inhibited tumor engraftment, and eliminated pre-existing tumors in mice." (PMID 35795660, 2022). "The expression of calreticulin (CRT) and CD47 in the tumor was evaluated, as they are key signals for the innate immune response." (PMID 36176603, 2022). "We lowered the tumor’s defense against macrophage-induced cell death and phagocytosis by blocking the “don’t-eat-me” signal, i.e., the immunoglobulin CD47, which was strongly expressed on tumor cells derived from K14-Cre BRCA1f/fp53f/f tumors." (PMID 36223740, 2022). "A SIRPγhi population displayed CSLC properties and transmitted the immune escape signal through sustaining CD47 expression in both SIRPγhi and SIRPγlo/– tumor cells." (PMID 35229723, 2022). "Binding to CD47, the SIRPα-Fc fusion protein can block the immunosuppressive CD47–SIRPα signal between macrophages and tumor cells as a decoy receptor and has demonstrated its immunotherapeutic efficacy in various tumors." (PMID 36080360, 2022). "We showed that extracellular vesicles, including exosomes, released from normal or tumor cells overexpressing CD47 (transgenic or native) can induce efficient CD47 cross-dressing on pig or human cells." (PMID 36454036, 2022).
tumor (continued). "Along similar lines, CD47-directed bsAbs target the CD47/SIRPα axis by blocking CD47 signalling and restoring phagocytosis of tumour cells by macrophages." (PMID 36555321, 2022). "Mechanistically, chemotherapy promotes macrophage secretion of interleukin (IL)−18, which upregulates LAT2 expression in tumor cells and consequently enhances glutamine and leucine uptake- and mTOR activity-dependent CD47 expression for tumor immune envision." (PMID 36274066, 2022). "The blockade of CD47-mediated inhibitory signaling by antibodies to CD47 also promoted tumor cell uptake by DCs and enhanced antitumor immune responses through cross-priming of CTLs in mice." (PMID 35454882, 2022). "A last anti-CD47 antibody has been tested on glioma stem cells: it is also effective to induce phagocytosis of these cells in vitro and in vivo, thereby limiting tumor growth." (PMID 35214076, 2022). "Highly expressed CD47 in multiple tumour cells inhibits phagocytosis by sending the “don’t eat me” signal." (PMID 35694254, 2022). "To explore the relationship between CD47 and tumor purity of cancers, we analyzed the ESTIMATE Score." (PMID 35697717, 2022). "It was then demonstrated that this IL-1RAP-mediated NF-κB activation induced the production of CD47 at the surface of tumor cells." (PMID 36499246, 2022). "Our data indicate that this strategy improved the tumor selectivity by reducing the interaction with CD47 expressed on normal cells." (PMID 35664753, 2022). "As expected, animal studies showed that BCH and the CD47 antibody treatment exhibited similar levels of tumor growth inhibition." (PMID 36274066, 2022). "Though future studies are still needed to better understand the intricate mechanisms recruiting NK cells, targeting CD47 has a therapeutic potential as a NK cell checkpoint in tumor micro-environment." (PMID 36081498, 2022). "In a study, anti-CD47 nanobody-expressing adenovirus reprogramed tumor immune microenvironment and showed excellent anti-tumor immunity." (PMID 36311790, 2022). "Second, VEGF is a potent immunomodulator acting in part through direct effects on T cells, a xenograft model has limited predictive power to evaluate how anti-VEGF/CD47 therapeutic combinations would regulate tumor growth in immune competent mice or humans." (PMID 35694254, 2022). "Tumor cell killing by myeloid cells can be improved by disrupting CD47/SIRPα interactions, for example with CD47 blocking antibodies." (PMID 36052078, 2022). "Considering the interaction between macrophages and tumor cells, the anti-tumor effects by blocking antibody was significantly better in CD47 than in PD-L1." (PMID 35869130, 2022). "In conclusion, our study indicates that the phagocytosis checkpoints of the PD1/PDL1 axis and CD47/SIRPα are enhanced in the tumor tissues of ICC patients and especially in HBV infection patients." (PMID 35317832, 2022). "Increasing evidence indicates that CD47 acts as a dominant “don’t eat me” signal, enabling tumor cells to escape from macrophage-mediated phagocytosis." (PMID 35860564, 2022). "Inhibition of SIRPα-CD47 interaction by anti-CD47 or anti-SIRPα antibody leads to a significant increase in cancer cell phagocytosis by macrophages and a decrease in tumor burden." (PMID 36135216, 2022). "The glycoprotein CD47 is often overexpressed on the surface of tumor cells and is usually considered a bad prognostic factor and a novel immunotherapeutic target." (PMID 35626032, 2022). "The silencing of CD47 induces microglia-mediated phagocytosis and the inhibition of growth of tumor cells." (PMID 36358792, 2022). "For that reason, several anti-CD47 therapies have been developed to block CD47-SIRPα signaling pathway and promote macrophage phagocytosis of tumor cells." (PMID 36171566, 2022). "cHL patients with high CD47 expression on tumor cells have an inferior event-free survival (EFS) compared with patients with low expression." (PMID 35626032, 2022).
tumor (continued). "SIRPα recognizes the elevated levels of CD47 on tumor cells and negatively controls effector function which prevents destruction of the cancer cells." (PMID 36369063, 2022). "Although M1 TAMs possess the ability to kill tumor cells, the clever tumor cells can express CD47, which binds to SIRPα on the macrophage surface to release the signal: “do not eat me”." (PMID 35859703, 2022). "Recent studies have shown that the CD47-SIRPα axis is a phagocytic checkpoint regulating macrophages and other innate immune cells, and a series of molecules that block the CD47-SIRPα axis are in clinical development for tumour therapy." (PMID 36310169, 2022). "Accordingly, it is feasible to leverage the difference in E3 ubiquitin ligase expression between erythrocytes and tumor cells to avoid hematological adverse reactions of CD47-SIRPα blockade." (PMID 36080223, 2022). "Secondly, anti-CD47 leads to tumor cell phagocytic uptake by antigen presenting cells and subsequent antigen presentation to T cells." (PMID 36081498, 2022). "In vivo, anti-CD47 antibody inhibited tumor engraftment and induced remission in ALL engrafted mice." (PMID 35769486, 2022). "For example, lentivirus carrying sequence of signal regulatory protein alpha (SIRPα), a ligand of CD47, and plasmid inserted with PD-1 sequence were transfected into different tumor cells." (PMID 35874757, 2022). "Initially, we evaluated CD47 expression level between the tumor and matched normal tissues across twenty cancer types via the TCGA database, and then verified by twenty-seven cancer types using the integrated database from GTEx and TCGA datasets." (PMID 35697717, 2022). "In vitro and in vivo studies demonstrated that CD47 blockade by a humanized anti-CD47 antibody (Hu5F9-G4) enhanced macrophage-mediated phagocytosis, improved survival, and reduced tumor burden in human GBM engrafted mice model." (PMID 35428347, 2022). "Although monotherapy with anti-CD47 or SIRPα has failed in clinical studies, anti-CD47 or SIRPα in combination with conventional therapies has shown significantly increased anti-tumor activities, especially in hematological malignancies." (PMID 35317832, 2022). "The binding of CD47 to its cognate receptor signal-regulatory protein alpha (SIRPα) on phagocytic cells leads to inhibition in the macrophage-mediated tumor cell phagocytosis." (PMID 35428347, 2022). "The binding of CD47 (cluster of differentiation 47) on tumor cells to SIRPα (signal-regulatory protein α) ligand on macrophages is a typical tumor escape mechanism." (PMID 36071472, 2022). "Researchers designed exosomes containing SIRPα variants as immune checkpoint blockers, thereby antagonizing the interaction between CD47 and SIRPα, inducing enhanced tumor phagocytosis, and triggering an effective anti-tumor T-cell response." (PMID 35890175, 2022). "A novel recombinant SIRPα-Fc fusion protein, IMM01, was constructed and produced using an in-house developed CHO-K1 cell expression system, and the anti-tumor mechanism of IMM01 targeting the CD47-SIRPα pathway was explored." (PMID 36384978, 2022). "The antibodies targeting CD47 and SIRPα, either alone or in combination with tumor cell-specific opsonizing antibodies and T-cell checkpoint inhibitors, have shown promise in several trials for various malignancies." (PMID 35874659, 2022). "The combination of complete CD47 disruption and tumor opsonization is thus not only synergistic but required for tumor control." (PMID 35454837, 2022). "When bone marrow-derived macrophages (BMDMs) expressing the biosensor were stimulated by tumor cells that highly express CD47, researchers observed the phosphorylation of SIRPα." (PMID 35794864, 2022). "Murine models were established by injecting athymic nude (Foxn1nu) or NOD scid gamma (NOD.Cg-PrkdcscidIl2rgtm1Wjl/SzJ), with prepared primary PDAC tumour samples to determine the effects of CD47 blockade." (PMID 35626020, 2022).